CD4 (CD4 molecule)
Diseases named in the same sentence as CD4 in open-access papers (continued):
Sharing a sentence is not in itself a finding about the gene and the disease.
dengue (continued). "In 2001, our group described a reduced frequency of CD4+ and CD8+ T lymphocytes and a poor ability for T‐lymphocyte proliferation in response to mitogens and dengue antigens in acute DENV‐infected patients, but re‐established in convalescence phase 48." (PMID 29282904, 2018). "Another recent study reports the presence of DENV/ZIKV cross-reactive CD4+ and CD8+ T cells in n = 4/5 and n = 2/6 dengue seropositive individuals, respectively, and in individuals who had received a live attenuated dengue vaccine." (PMID 30327651, 2018). "In line with previous studies, DENV capsid elicited IFN-γ responses mainly in CD4+ T cells and to a minor extent in CD8+ T cells of dengue-immune donors." (PMID 30327651, 2018). "Indeed, we found that stimulated IFN-γ-producing CD4 TEMRA cells in donors with secondary DENV infections displayed a predominant GPR56+ phenotype, further supporting the notion that CD4 TEMRA subsets with cytotoxic functions may protect the host from severe dengue diseases." (PMID 29133794, 2017). "The median CD4 counts 6 months before and after dengue diagnosis were 123 cells/mm3 (IQR = 79–303 cells/mm3) and 144 cells/mm3 (IQR = 74.5–251 cells/mm3), with median lowest CD4 count of 45 cells/mm3 (IQR = 37–75.5 cells/mm3)." (PMID 25825389, 2015). "Several observations suggest a massive T-cell activation during DHF, producing cytokines (interferon γ, interleukin 2, TNF α) and infected cell lysis by CD4+ and CD8+ dengue specific lymphocytes are responsible for plasma leakage." (PMID 25242847, 2014). "Some studies have identified a distinct subset of dengue-specific CD4+ T cells that mostly do not show abnormal cytokine expression but display cytotoxic properties." (PMID 40469309, 2025). "During dengue virus infection, there is an increased expression of CCR5 on CD4." (PMID 38674183, 2024). "Hence, in this study we first focused on addressing this question by compiling known dengue-specific CD8 and CD4 T cell epitopes worldwide and aligning these with 107 published full-length polyprotein sequences of dengue virus isolates available from India." (PMID 38793612, 2024). "As shown previous experiment, we observed a higher IFN-γ response in DSV4 immunized mice and thus, here, we have looked at whether the viral dengue vaccine candidate, DSV4, induces the TH1 CD4+ T cells." (PMID 36926350, 2023). "Viral coinfections could even be worse especially for dengue and HIV as the two viruses share the common target cells such as CD4 positive cells." (PMID 33861747, 2021). "Similarly, augmented expression of CX3CR1 also tends to favor CD4+ CTL transmigration into inflamed tissue, as exemplified in Dengue, where virus-specific CX3CR1 CD4+CTLs mediate protective cytotoxicity." (PMID 34721397, 2021). "Both CD4 and CD8 T-cell activation have been shown in dengue natural infection and vaccination." (PMID 34031380, 2021). "Transcriptomic analysis of dengue patient blood showed a positive correlation of monocytes, macrophages, DCs, and neutrophils, and a negative correlation of NK cells, CD4+ T cells, CD8+ T cells, and B cells with viral loads." (PMID 33072626, 2020). "In addition to humoral immunity, we and others have found that durable CD4+ and CD8+ T cell responses are induced by tetravalent live attenuated dengue vaccination." (PMID 33377126, 2020). "Furthermore, a proportion of the responding CD4+ and CD8+ T-cells tended to be Th0/Th1-biased and multifunctional, as seen for other live-attenuated dengue vaccines in primed and flavivirus-unprimed subjects." (PMID 30829100, 2019). "Dengue induces a number of CD4+ T‐ and CD8+ T‐cell epitopes to both structural and nonstructural proteins recognized in mice and humans." (PMID 29223138, 2018). "Notably, cytotoxic CD4 T cells are readily detectable following DENV infection and correlate with enhanced protection against dengue disease." (PMID 28003809, 2016).
dengue (continued). "The development of DENV-specific CD4+ and CD8+ T-lymphocyte responses, and the activation and contraction of antiviral CD8+ T lymphocytes in the defervescence and convalescence phases of dengue fever has previously been documented." (PMID 23967362, 2013). "Interestingly, in addition to these cells, we found CsA-resistant IFN-γ producing T cells (CD4+T = 26.9 ± 3.6% and CD8+T = 20.3 ± 2.1%) implying the existence of activated bystander T cells in response to dengue antigen in vitro." (PMID 20854672, 2010). "Similarly, transcriptional profiles of asymptomatic DENV-infected individuals featured increased T cell activation relative to clinical dengue counterparts, and multi-functional CD4+ and CD8+ T cells have been found at higher frequencies in outpatients compared to hospitalized dengue cases." (PMID 37055751, 2023). "Additionally, protein immunodominance for both CD4 and CD8 T cells in Dengue virus infection is also a function of multiple exposure of Dengue infection, and that tends to skew protein immunodominance toward epitopes highly conserved across different Dengue serotypes." (PMID 34212022, 2021). "Furthermore, CLA expression on circulating DENV-specific CD4+ and CD8+ T cells appeared to correlate with their skin-homing capacity, as these cells were detected at high frequencies in the skin of patients with acute dengue." (PMID 32549226, 2020). "It is not clear whether altered CD4/CD8 T ratios could lead to dengue severity in ART treated HIV patients." (PMID 32286360, 2020). "Interestingly, patients coinfected with dengue and HIV presented increased expansion of CD8+ related to CD4+ T cells and increased activation of both T cell subsets compared to dengue patients without HIV coinfection." (PMID 31068600, 2019). "Consequently, the knowledge of dominant epitopes targeted by CD4+ and CD8+ T cells might be essential for elucidating the mechanism involved in protection, resulting in more effective vaccines against dengue as well as against other flaviviruses." (PMID 31333657, 2019). "In addition, a correlation of CD4+Foxp3+ Tregs with the outcome of flavivirus infection has been reported; Treg expansion but not absolute level was lower in children with severe dengue disease." (PMID 27439902, 2016). "However, it has been established in the literature that CD4+ T cells are not required for generation of Dengue vaccine specific nAb or CD8+ T cell responses." (PMID 27703172, 2016). "Importantly, accumulating studies demonstrate that cytotoxic CD4 T cells develop following DENV infections and may play a crucial role in protecting the host from severe dengue disease." (PMID 28003809, 2016). "The proportion of CD4 T cells expressing CD38 was not altered in dengue cases compared to controls." (PMID 22815692, 2012). "Since the principal dengue target cells are monocytic cells including monocyte, macrophage and dendritic cells and HIV infects macrophage and CD4+ T cells, it may be expected that dengue and HIV infections directly stimulate relevant human cells to make IFNα, but not IFNβ." (PMID 21206915, 2010). "In conclusion, we provided evidence that SD-EV modulated CD4 carrying PD-1 and CD44 when interacting with EC significantly affected endothelial properties through direct interaction or via secretome and may be significant in dengue-mediated endothelial dysfunction." (PMID 39745465, 2025). "Moreover, among subjects with secondary DENV infections, CD4+ TEMRA cells that produced IFN-γ after antigenic stimulation predominantly exhibited a GPR56+ phenotype, corroborating the involvement of cytotoxic CD4+ TEMRA subsets in HLA-dependent protection against severe dengue disease." (PMID 32549226, 2020). "However, the results showed here that peptide 27 despite of appearing in all predictions and curiously also being a putative CD4+ T-cell epitope, does not differentiate well between dengue 3 and non-dengue patient serum but can be a potential candidate as a marker for serotype diagnostic." (PMID 19826631, 2009).
dengue (continued). "For example, based on our data, we expect that 27% of the global CD4 epitopes, and 13% of the global CD8 epitopes, will not function, based on the analysis of dengue-specific T cell responses in India." (PMID 38793612, 2024). "We do not know which of the dengue-specific experimentally validated CD8 and CD4 T cell epitopes reported from other parts of the world remain conserved in the circulating dengue viruses from India." (PMID 38793612, 2024). "Human anti-dengue T cell response is targeted majorly against non-structural proteins NS1, NS3, NS4b and NS5 by CD8+ T cells, while CD4+ T cells target structural proteins capsid, envelope, along with NS1, NS3, NS2 and NS5 dengue protein." (PMID 36926350, 2023). "Moreover, CD4 + and CD8 + T cells increased after a single dose of a tetravalent live-attenuated dengue vaccine were directed to the same region of non-structural protein antigens as T cells from a naturally infected human." (PMID 33072068, 2020). "We observed CD4+ and CD8+ T cell subset kinetics during the course of natural infection in dengue patients; however, we did not distinguish DENV specific T cell populations that could be analyzed by tetramers." (PMID 33072068, 2020).
Sjögren’s syndrome (96 papers, 2007 to 2026). "Based on association with Vβ20-1/Vα17-1/CD4 + T cells with Sjögren’s syndrome tissue damage, we chose to coordinate nucleotide analogues with TCR bearing SMX docked sites." (PMID 36172593, 2013). "To assess the types of salivary gland (SG) T cells contributing to Sjögren’s syndrome (SS), we evaluated SG T cell subtypes for association with disease features and compared the SG CD4+ memory T cell transcriptomes of subjects with either primary SS (pSS) or non-SS sicca (nSS)." (PMID 32650575, 2020). "Interestingly, CD4+ T cells from scurfy lymph nodes can also induce myositis and inflammation of the salivary glands (resembling Sjögren’s syndrome) upon transfer into susceptible (RAG-1-knockout) recipients." (PMID 25890083, 2015). "Histological features of Sjögren’s syndrome, on the other hand, include lymphocytic infiltration in the interstitial tissue, predominantly composed of CD4 T lymphocytes, along with interstitial fibrosis and tubular atrophy as the disease progresses." (PMID 40130134, 2025). "In the subgroup of patients with Sjögren’s syndrome, CD4 T lymphocytes were predominant, with 15 cases out of 16 with CD4:CD8 ratios equal to or greater than 2:1." (PMID 40257948, 2025). "In a clinical study, miR-26a, miR-146a, and miR-155 were shown to be differentially expressed in CD4 T and B lymphocytes of the patients with primary Sjögren’s syndrome." (PMID 39934489, 2025). "Glandular atrophy was associated with the development of polyautoimmunity and a predominance of CD4 T lymphocytes in patients with Sjögren’s syndrome." (PMID 40257948, 2025). "The interaction between TNFSF8 and TNFRSF8-triggered signaling in CD4+ T cells is involved in the pathogenesis of Sjögren's Syndrome." (PMID 39170389, 2024). "CD70 is overexpressed in SLE, SCLE, SSc, and primary Sjögren’s syndrome (pSS), because of demethylation of its promoter regulatory regions in CD4+ T cells." (PMID 36980827, 2023). "Inhibition of glycolysis attenuates CD4 T cell proliferation and autoimmune responses in Sjogren’s syndrome." (PMID 36672927, 2023). "Sjogren’s syndrome is a chronic autoimmune disease characterized by highly activated CD4+ T cells in the salivary glands." (PMID 36195846, 2022). "LTA gene is shown to be hypomethylated in CD4 T-lymphocytes of patients with primary Sjögren’s syndrome (pSS)." (PMID 35813204, 2022). "Our previous study pointed out that SS-1 inhibits Th1 (CD4+ IFN-γ+ and CD4+ TNF-α+ cells) and Th2 (CD4+ IL-4+ c cells) polarization of mouse spleen cells and T cell proliferation in Sjögren’s syndrome." (PMID 34200223, 2021). "In patients with Sjogren’s syndrome, the changes of oral microbiome in glandular and mucosal tissues brought about activated plasma cell and CD4+ cells that ruined the secretory acini of salivary glands." (PMID 34887848, 2021). "The ICOS+PD-1+ cTfh cells and IL-21 producing CD4+CXCR5+PD-1+ T cells were also shown to be significantly higher in patients with Sjögren syndrome." (PMID 33465845, 2021). "Histopathologically, Sjögren syndrome mainly features extensive CD4+ T cells and antibody-secreting B cell infiltration, which together cause the destruction of salivary glands." (PMID 34630072, 2021). "Differential methylation of immune genes has been a consistent theme observed in Sjögren’s syndrome (SS) in CD4+ T cells, CD19+ B cells, whole blood, and labial salivary glands (LSGs)." (PMID 33886574, 2021). "Primary Sjögren’s syndrome (pSS) is a chronic systemic autoimmune disease which has focal lymphocytic infiltration including a majority of CD4+ T cells." (PMID 34641948, 2021). "A critical role for subsets of CD4+ T cells has been described in DED as well as Sjögren's syndrome." (PMID 30158831, 2018). "Sjögren’s Syndrome has long been considered a Th1-mediated disease elicited through the transformation of naïve CD4+ T cells into Th1 lymphocytes." (PMID 30453645, 2018).
Sjögren’s syndrome (continued). "In patients and in the NOD mouse model of Sjögren’s syndrome, lymphocytic infiltrates are known to consist of CD4 and CD8 T cells in the lacrimal glands." (PMID 29068389, 2017). "Historically, primary Sjögren's syndrome (pSS) was thought to be a T helper (h) 1 driven disease due to the predominance of CD4+T lymphocytes and their products in target organs and peripheral blood of patients." (PMID 26060357, 2015). "According to recent studies, the CD4+CD25lowGITR+ cell is a novel human CD4+ T-cell population with regulatory activity and expanded in patients with Sjögren’s syndrome or SLE; the results of these studies provide new insight for our follow-up study." (PMID 25429429, 2014). "Furthermore, it has been observed in patients with Sjögren’s syndrome that cDC2 increases the proliferation of CD4+ T cells which subsequently target tissues." (PMID 39769367, 2024). "Role of CD4+ T cells in the pathogenesis of SS (pss:Primary Sjögren’s Syndrome)." (PMID 36389806, 2022). "For example, overexpression of CD4+ GZMB+ CTL cells were found in Sjögren’s syndrome." (PMID 35958546, 2022). "This study examined the hypothesis that oral dysbiosis modulates the antigen-presentation function of SGECs, which regulates CD4 T cell proliferation in primary Sjögren’s syndrome (pSS)." (PMID 33707430, 2021). "A defect of this mechanism, as seen in Sjögren’s syndrome, could be a reason for the accumulation of CD4 T cells." (PMID 34959486, 2021). "Neither proportions nor numbers of SG CD4+ or CD8+ T cells correlated with the European Sjögren’s syndrome Disease Activity Index (ESSDAI), in line with our prior observations showing that the degree of CD4+ T cell clonal expansion associated with reduced salivary flow but not ESSDAI." (PMID 32650575, 2020). "The cTfh to cTfr ratio indicated ectopic lymphoid structure formation in minor salivary gland, strongly associated with B cell, CD4+ T cell, and PD-1+ICOS+ T cell infiltration in minor salivary gland and allowed discrimination between Sjogren’s syndrome patients and healthy donors." (PMID 31382877, 2019). "CD4+ T lymphocytes comprise majority of the glandular infiltration in primary Sjogren’s syndrome." (PMID 28469828, 2017). "In conclusion, the present data, together with those previously published on patients with primary Sjӧgren syndrome, suggest that CD4+CD25low/-GITR+ cells are expanded pTregs in response to an effector/Treg imbalance and are able to control, at least in part, the disease." (PMID 25256257, 2014). "However, a more recent report argues that the numbers of circulating CD4+CD25high regulatory T cells in patients with Sjogren syndrome decrease." (PMID 19046457, 2008). "Indeed, there is evidence that the colonization of germ-free mice with the GM derived from Sjögren’s syndrome patients decreases the abundance of CD4+ forkhead box P3 (FOXP3)+ Treg cells in cervical lymph nodes and promotes corneal barrier damage following dry eye induction." (PMID 37686143, 2023). "Given that chronic IFN signalling is a central pathogenic factor in both primary Sjogren’s syndrome as well as in SLE, these findings could therefore provide a mechanistic rationale underlying the increased frequency of CD57+ CD4+ CTLs in blood of patients with active IFN responses." (PMID 35509371, 2021). "However, whether IL-27 participates in pathological progress of Sjögren syndrome (SS) through regulating CD4+IL-10+ T cells remains unknown." (PMID 32849596, 2020). "Although we did not do any correlation with CD4+ T cell numbers, Levine and collaborators showed that lower levels of miRNA 199a may be associated with a decline in purified T and B lymphocytes from patients with primary Sjogren’s syndrome." (PMID 35594307, 2022). "T cell infiltration and upregulation of CD3, CD4, and CD8 as well as lymphocyte activation markers CD11a and HLA-DR are found in conjunctival biopsy specimens among Sjogren syndrome-related and non-Sjogren syndrome-related DED." (PMID 31443274, 2019).